IL1A (interleukin 1 alpha)
Diseases named in the same sentence as IL1A in open-access papers (continued):
Sharing a sentence is not in itself a finding about the gene and the disease.
keloid (11 papers, 2017 to 2025). An irregularly shaped, elevated mark on the skin caused by deposits of excessive amounts of collagen during wound healing. "Ogawa (2017) suggested that keloids and hypertrophic scars are derived from an abnormal inflammatory reaction in the skin since proinflammatory factors, including IL-1α, IL-1β, IL-6, and TNF-α, are associated with keloid formation." (PMID 33282860, 2020). "IL-6, IL-1β, IL-1α, and IL-8 are highly expressed in keloid fibroblasts, and induce the expression of TGFβ1 or render scars more sensitive to external stimuli, thus contributing to the continuous scar expansion and keloid formation." (PMID 38338767, 2024). "One report identified up-regulation of the proinflammatory cytokines, IL-1α, IL-1β, IL-6, and TNFα, in keloid fibroblasts." (PMID 33329590, 2020). "IL-1α, IL-1β and TNFα mRNA expression levels decreased in pathologic scars compared to healthy skin, especially IL-1β in keloid scars." (PMID 30765798, 2019). "In addition, proinflammatory factors, for example interleukin (IL)-1α, IL-1β, IL-6, and tumor necrosis factor-α are overexpressed in keloid, which proposes that the gene expression of these factors in the skin are responsive to trauma." (PMID 32850775, 2020). "Moreover, proinflammatory factors, such as interleukin (IL)-1α, IL-1β, IL-6, and tumor necrosis factor-α are upregulated in keloid tissues, which suggests that, in patients with keloids, proinflammatory genes in the skin are sensitive to trauma." (PMID 28287424, 2017). "This is supported by the upregulation of pro-inflammatory cytokines such as interleukin (IL)-1α, IL-1β, IL-6, and tumour necrosis factor (TNF)-α in keloid tissues." (PMID 39119435, 2024). "Additionally, elevated levels of pro‐inflammatory cytokines such as IL‐1α, IL‐1β, IL‐6, and TNF‐α in keloids contribute to chronic inflammation by increasing fibroblast proliferation, inhibiting apoptosis, and driving ECM synthesis." (PMID 41049267, 2025). "Inflammatory factors, such as IL-1α, IL-1β, IL-6, and TNF-α, are upregulated in keloid tissues, suggesting that keloids may be considered inflammatory skin disorders, specifically of the reticular dermis, rather than tumors." (PMID 39119435, 2024). "However, its persistent overexpression, as seen in keloids and hypertrophic scars, likely due to high TGF‐β and IL‐1α signaling, may contribute to dermal fibrosis, characterized by excessive α‐SMA‐positive (myo)fibroblasts, increased ECM deposition, and fibroblast hyperproliferation." (PMID 40279507, 2025).
liver fibrosis (11 papers, 2012 to 2025). "IL-1α deficiency can reduce the risk of liver fibrosis in NASH by reducing the level of CXCL1." (PMID 34853322, 2021). "IL-1α is a multifunctional cytokine and enhances collagen synthesis by increasing the proliferative activity of perisinusoidal cells and has been implicated in the pathogenesis of hepatic fibrosis." (PMID 26448742, 2015). "IL-1α and IL-1β act synergistically in promoting development of liver fibrosis, as shown in a study that blocking the expression of either of them in vivo was sufficient to protect mice from developing steatohepatitis." (PMID 32085494, 2020). "IL-1α or IL-1β knock-out mice are also less likely to develop liver fibrosis in animal models of steatohepatitis." (PMID 27046197, 2016). "The identification of the Hepatic Fibrosis/Hepatic Stellate Cell Activation pathway (identified by Vegfa, Il1a, Tgfb1, Tgfa, Il1b, and Pgf) is interesting, as the polarization of M2 macrophages is a critical component of this pathology." (PMID 24156623, 2013). "Profibrotic factors such as IL-1α and IL-1β that play a role in liver fibrosis development, and TNF-α which is an essential cofactor of IL-13 to induce the expression of IL-13Rα2, were upregulated." (PMID 24143891, 2013). "Recent studies on the pathogenesis of liver fibrosis have indicated that the increased secretion of IL-1α/β or TNF-α by macrophages in liver fibrosis mouse models using gene knockout technology enhanced the expression of pro-fibrotic genes in HSCs, thereby exacerbating liver fibrosis." (PMID 41296792, 2025). "Our data indicate that significant upregulation of IL1A and IL1B from quiescent HSC due to HCV/HIV co-infection might be an early inflammatory response contributing to enhanced HSC activation leading to hepatic fibrosis." (PMID 30679661, 2019).
peritonitis (11 papers, 2013 to 2025). Inflammation of the peritoneum (tissue that lines the abdominal wall and covers most of the organs in the abdomen). "A dominant role of IL-1α compared to IL-1β has been demonstrated in nano-TiO2-induced peritonitis and lung neutrophilic inflammation by using IL-1R-, IL-1α- or inflammasome component-deficient mice." (PMID 25497724, 2014). "The in vivo model of MSU-induced peritonitis allowed to evidence that both IL-1α and IL-1β production was reduced at an early phase in CalpTG mice, suggesting that calpains actually promote IL-1α and IL-1β synthesis in response to cellular stress in vivo." (PMID 28808241, 2017). "In an experiment in which lysate cell were injected into the peritoneal cavity of mice in a model of peritonitis, an inflammatory response and neutrophil infiltration occurred in an IL-1A dependent manner." (PMID 27918732, 2017). "Using a sterile peritonitis model, we examined the effect of IL-1R2 loss without the high level of IL-1R2 in the circulation, which showed increased neutrophil recruitment in response to IL-1α in R2–/– mice." (PMID 38329807, 2024).
Cachexia (10 papers, 2011 to 2024). Severe weight loss, wasting of muscle, loss of appetite, and general debility related to a chronic disease. "Administration of IL-1α was found to induce cachexia together with anorexia by causing accelerated SM protein wasting in a rat model." (PMID 32195193, 2020). "Levels of Tumor Necrosis Factor (TNF), IFN-γ and IL-1α, three other cytokines frequently associated with cachexia, were significantly elevated as well." (PMID 21799891, 2011). "Cytokines, including Tumor Necrosis Factor (TNF)/cachectin, interleukin (IL)-1α, IL-1β, interferon-γ, and IL-6 have been implicated in cachexia both through experimental manipulation in mouse models and by association of serum levels in patients with cachexia." (PMID 21799891, 2011). "Although the translational importance of IL-1α in our RSV model is yet unclear, the IL-1α monoclonal antibody, MABp1, has shown prominent clinical benefits in a trial treating cancer-associated cachexia." (PMID 38382577, 2024). "In current clinical studies, good progress has been made in improving cachexia with therapies that counteract key cachexia factors such as IL-6, IL-1β, and IL-1α." (PMID 35740622, 2022). "As an alarmin, bioactive IL-1α can be released via a broad range of cell damage or death inducers, and future work will be necessary to determine the source and mechanism of release of IL-1α during cachexia." (PMID 32973293, 2020). "A more recent study demonstrated how IL-1 beta (IL-1β) increased SM catabolism in a rodent model of CC by promoting a cachexia-associated gene expression pattern in the hypothalamic–pituitary–adrenal (HPA) axis, differently from IL-6 and IL-1α." (PMID 32195193, 2020). "We also evaluated expression of IL-6, TNF-α, IFN- γ, IL-1α, and IL-1β because these inflammatory cytokine are frequently observed in cachexia as well as fibrotic diseases." (PMID 32973293, 2020). "Known factors involved in cachexia, IL-1α, IL-1β, IL-6, IL-8 and TNFα are all proteins that may be produced by the innate immune cells or other non-immune cell types such as epithelial cells or stromal cells." (PMID 30513792, 2018). "Therefore, although we observed decreases in IL-1α, IL-4, and IL-6 that would putatively promote an anti-inflammatory phenotype and mitigate cachexia, it is unclear whether the counter-effect of decreased IL-1RA plays a role in such discrepancies with lean body mass across studies." (PMID 36056179, 2022). "IL-1α, TNF, IL-8, and IL-10 were significantly elevated in cachexia patients but IL-1β and IL-6 were not significantly elevated in the cachexia patients." (PMID 36358681, 2022).
co-infection (10 papers, 2013 to 2025). "Significant increases of IL-6, IL-8, TNFα, and IL-1α were observed in the vWT and S. suis co-infection group, compared to the vWT single-infection group, indicating that co-infection of PRRSV-2 and S. suis enhanced the proinflammatory cytokine expressions." (PMID 38547254, 2024). "In contrast, the co-infection of vL126A/ΔNLS with S. suis induced significantly lower-level expressions for IL-6, IL-8, TNFα, and IL-1α in comparison with the vWT and S. suis co-infection." (PMID 38547254, 2024). "Co-infection also induced a divergence with regard to the production of IL-1 in which Il1b expression was highly increased in F4/80low MΦ while Il1a expression was dramatically increased in F4/80high MΦ." (PMID 28334040, 2017). "Specifically, production of key proinflammatory cytokines (e.g., IL-1α and IL-1β), chemokines (e.g., CCL20 and CXCL8), and VEGFA was markedly downregulated during co-infection with either HCMV variant, reflecting the known synergistic interference between the two pathogens." (PMID 40980889, 2025). "In addition, a reduced level of mRNA expression of the cytokines IL-1α, IL-6 and IFNα was observed during co-infection compared to single infection." (PMID 39772252, 2024). "In particular, IL-1α was decreased in co-infection with SARS-CoV-2 and increased with AdV2." (PMID 39772252, 2024). "In this study, we additionally report the regulation of proinflammatory (IL1-α, IL1-β, IL6, IL8, IL18, and TNF-α) and regulatory (IL10, IL22, IL23, and IL33) cytokines associated with single-PDCoV and -PEDV infection, as well as PDCoV/PEDV co-infection." (PMID 36376395, 2022). "In all conditions,IL1α, a pro-inflammatory alarmin that is released by enterocytes duringintestinal injury,was elevated in all groups and reached significance in Giardiainfected mice (~30-fold) and robustly increased in co-infection (~80-fold)." (PMID 28750066, 2017). "This might suggest that the performance of at least EGF and IL-1α might be influenced by HIV co-infection." (PMID 23691173, 2013). "Low but detectable increases in IL-1α, IL-4, MIP-1α, MIP-1β, TNF, fractalkine and RANTES occurred upon Mtb infection and Mtb/HIV-1 co-infection, depending of the cell type." (PMID 40420159, 2025). "Thus, IL-1α, IFN-α and IL-6 mRNA expression were measured at 3 hpi and at 24 hpi in co-infection." (PMID 39772252, 2024). "Thus, in our study, modulation of the mRNA expression of the cytokines IL-1α, IL-6 and IFNα by H1N1pdm09 or SARS-CoV-2 may have promoted enhanced viral replication during co-infection." (PMID 39772252, 2024).
epilepsy (10 papers, 2012 to 2024). A brain disorder characterized by episodes of abnormally increased neuronal discharge resulting in transient episodes of sensory or motor neurological dysfunction, or psychic dysfunction. "Some studies have reported polymorphisms in IL-1α, IL-1β, and IL-1Ra in subjects who develop epilepsy as adults." (PMID 30459597, 2018). "In contrast to the epilepsy-associated increase in IL-1α mRNA in patients of both genotypes, IL-1α protein measured by Western blot showed much greater elevation of IL-1α protein in APOE ε3,3 patients than that in APOE ε4,4 patients." (PMID 22502727, 2012). "The “Epilepsy-only” patients had significantly higher serum and mRNA levels of IL-1α, β, IL-2,6,8, and TNF-α compared to the controls and the “Cannabis+Epilepsy” group (p = 0.0001)." (PMID 31757102, 2019). "The IL-1 family consists of 7 agonists (e.g., IL-1α and β) and 3 receptor antagonists, and amongst these the IL-1β isoform has been the most commonly studied in the brain injury and epilepsy settings." (PMID 28086980, 2017). "In the clinical setting, peripheral blood mononuclear cells collected from epilepsy patients exhibited greater production of IL-1α in response to stimulation in vitro compared to cells from non-epileptic controls." (PMID 28086980, 2017). "Our finding of elevated synthesis of IL-1α in the temporal lobe of epilepsy patients compared to that in neurologically normal controls confirms an earlier report of elevated IL-1α protein and accompanying glial activation and other neuroinflammatory changes." (PMID 22502727, 2012). "Overall, patients with epilepsy had IL-1α mRNA levels that were five-fold higher than those of neurologically normal controls." (PMID 22502727, 2012). "For instance, the miRNA rno-let-7c-5p is dysregulated in human epilepsy and inferred mRNA targets present in multiple other resources include Cux1 (Cut like homeobox 1), Il1a (Interleukin 1 Alpha), Msn (Moesin), Nat8l (N-acetyltransferase 8 like) and Wapl (WAPL cohesin release factor)." (PMID 38961125, 2024). "Thus, inflammatory cytokines like IL-1α, IL-1β, TNF-α and IL-1α facilitate the initiation of seizures and subsequent progression to epilepsy." (PMID 36945556, 2023). "In line with the role ofinflammatory agents in epilepsy, the induction of IL1α, TNF-α, and IL-6 has been shown in both neuronsand glia before epilepsy onset." (PMID 33650824, 2021). "These elevations in the levels of both IL-1α mRNA and protein were accompanied by an APOE ε3,3 genotype-specific increase in βAPP expression in epilepsy patients compared to controls (APOE ε3,3 = 42 ± 11 vs APOE ε4,4 = 20 ± 11; and control = 21 ± 7; P = 0.03)." (PMID 22502727, 2012). "The serum and gene expression of the inflammatory cytokines—IL-1α, IL-1β, IL-2, IL-6, IL-8 and TNF-α—showed the highest levels among the “Epilepsy-only” group followed by lower levels in the epilepsy–cannabis users and finally the lowest levels in the healthy controls." (PMID 31757102, 2019). "Other members of the IL-1 family such as IL-1α have also been reported to up-regulate in brain tissue after TBI, but are not related to the prognosis of TBI or epilepsy." (PMID 34122298, 2021).
schizophrenia (10 papers, 2016 to 2024). A major psychotic disorder characterized by abnormalities in the perception or expression of reality. "Further research is needed to evaluate the association between the IL-1a gene and the risk of schizophrenia, as well as their correlations in different populations." (PMID 35743957, 2022). "The IL1A -889 G>A polymorphism was found to be associated at both allelic and genotypic level with schizophrenia." (PMID 27177030, 2016). "Notably, this study represents the first prediction of the interactions of IL-1α, IL-1β, and IL- 1RA proteins, taking into account the presence of single-nucleotide polymorphisms associated with schizophrenia in the sequence of the corresponding genes." (PMID 38988763, 2024). "We found an association of IL1A -889 A allele and AA genotype with schizophrenia in our population." (PMID 27177030, 2016). "Although some genetic studies have suggested that IL1A is associated with susceptibility to SZ, others have provided differing insights and indicated that its dysfunction may be related to the pathogenesis of schizophrenia." (PMID 39544374, 2024). "Thus, the association of IL1A high producer genotype AA and allele A with schizophrenia may imply alterations in the early developmental process of brain or neural development or modify the metabolism of neurotransmitters." (PMID 27177030, 2016). "Using Mendelian Randomization analysis, we found nine inflammatory proteins, including IL-1A and TNF-α, that contribute to the genetic susceptibility of schizophrenia." (PMID 39544374, 2024). "The decreased expression of IL1-α and interferon-gamma-inducible protein (IP)-10 was found in patients with schizophrenia." (PMID 35743957, 2022). "Patients with a continuous course of schizophrenia showed statistically significantly higher levels of IL-12p70 (p = 0.019), IL-1α (p = 0.046), and IL-1β (p = 0.035) compared with patients with an episodic course." (PMID 36556337, 2022). "Patients with a continuous course of schizophrenia showed statistically significantly greater levels of IL-12p70 (p = 0.019), IL-1α (p = 0.046), and IL-1β (p = 0.035) compared to patients with an episodic course." (PMID 36556337, 2022). "In our study, patients with a continuous course of schizophrenia had elevated levels of proinflammatory cytokines (IL-12p70, IL-1α, and IL-1β) as compared with patients with an episodic course." (PMID 36556337, 2022). "Nonetheless, no relevant research has been found on the inhibitory treatment of IL-1a in schizophrenia." (PMID 35743957, 2022). "This dendrogram showed that the expression patterns of IL-1α and IP-10, which were significantly reduced in the schizophrenia group in this study were similar." (PMID 33815179, 2021). "The present study provides evidence of strong independent associations of pro-inflammatory cytokine genes IL1A, IL6, TNFA, and IFNG with schizophrenia and their interactions in Dravidian South Indian population." (PMID 27177030, 2016). "In the present study, we report significant association of SNPs in pro-inflammatory cytokine genes IL1A, IL6, TNFA, and IFNG with schizophrenia in the Malayalam-speaking Dravidian population of India." (PMID 27177030, 2016). "Among cytokine genes, significant association was observed with pro-inflammatory cytokine gene polymorphisms of IL1A, IL6, TNFA, and IFNG with schizophrenia in our study population." (PMID 27177030, 2016). "Moreover, IL-1α has a nutritional effect on host dopaminergic neurons in vivo and in vitro, which is closely related to the pathophysiology of schizophrenia." (PMID 35743957, 2022). "However, an elevated level of IL-1α was found in patients with schizophrenia with metabolic syndrome even after 6 weeks of treatment with atypical antipsychotics." (PMID 35743957, 2022).
schizophrenia (continued). "Schizophrenia has also been shown to be associated with polymorphisms of numerous genes responsible for the synthesis of such cytokines as IL1A, IL1B, IL10 and IL6, which are genes for, respectively, IL-1α, IL-1β, IL-10 and IL-6." (PMID 34501305, 2021). "Thus, the expression of IL-1α and IP-10 in the brain may be suppressed in the chronic phase of schizophrenia observed in postmortem brain." (PMID 33815179, 2021). "Previous findings showed that there is contradicting evidence (elevation, decrease, or no change) regarding levels of proinflammatory cytokine IL-1a in plasma and cerebral spinal fluid of patients with schizophrenia." (PMID 35743957, 2022). "By diagnosis, there was a trend toward an increase of IL1A mRNA in schizophrenia cases (t = −1.731, df = 52, p = 0.089) and IL17RA mRNA was significantly increased in schizophrenia cases compared with control subjects (t = −3.952, df = 54, p < 0.001) (data not shown)." (PMID 31168068, 2021). "However, a meta-analysis reported no alterations in the gene expression of IL-1α and IP-10 in patients with schizophrenia." (PMID 33815179, 2021).